RGPD5 (RANBP2 like and GRIP domain containing 5)
Synonyms: RGP5; BS-63; DKFZp686I1842; BS63; HEL161
Tractability: PROTAC: ubiquitination databases record sites on it.
Gene: Protein-coding gene on chromosome 2 (109,792,758 to 109,857,705, forward strand). Ensembl gene ENSG00000015568.
Subcellular location: Cytoplasm
Subcellular location (Human Protein Atlas): Nuclear membrane; Vesicles
Gene Ontology:
Molecular function: protein binding; SUMO transferase activity
Biological process: NLS-bearing protein import into nucleus; nuclear export
Cellular component: nuclear pore; cytoplasm; Golgi apparatus
Homologues: Orthologues: zebrafish ranbp3a (5% identical), Drosophila melanogaster RanBP3 (5% identical). Paralogues in human: RGPD6 (100% identical), RGPD8 (99% identical), RGPD3 (95% identical), RGPD4 (94% identical), RGPD1 (93% identical), RGPD2 (93% identical), RANBP2 (84% identical), RANBP3 (7% identical), RANBP3L (4% identical), RANBP1 (4% identical).
Diseases named in the same sentence as RGPD5 in open-access papers:
RGPD5 is named in the same sentence as 3 diseases in open-access papers, as found by Europe PMC text mining. Sharing a sentence is not in itself a finding about the gene and the disease. The quoted sentences say what the papers report.
cancer (1 paper, 2025). A tumor composed of atypical neoplastic, often pleomorphic cells that invade other tissues. "Upregulation of RGPD6, RGPD5, RGPD8, RGPD2, NUP210L, and PLCL1 has been observed in invasive tumors, implicating this functional network in the remodeling of ECM stiffness and integrin signaling, both of which enhance cancer cell migration." (PMID 40370715, 2025).
RGPD5 also shares sentences with these, for which no sentence is quoted: lip (1 paper); Talipes equinovarus (1).